HIF1A (hypoxia inducible factor 1 subunit alpha)
Diseases named in the same sentence as HIF1A in open-access papers (continued):
Sharing a sentence is not in itself a finding about the gene and the disease.
cancer (continued). "We further verified the effect of the HIF-1α/miR-210 pathway on the metastasis of cancer cells and CAFs in the process of MSCs being induced into CAFs in the subcutaneous xenograft model of CRC." (PMID 34631221, 2021). "HIF-1A is another master regulatory switch that plays a central role in cancer progression by controlling broad signaling pathways involved in metabolism, survival and angiogenesis." (PMID 34209094, 2021). "The accumulation of succinate and fumarate due to defects in SDH and FH leads to the inhibition of prolyl hydroxylase enzymes (PHD), stabilization of HIF-1α and subsequent acceleration of glycolysis in cancer cells." (PMID 34208645, 2021). "Several reports have demonstrated that ROS stabilize HIF‐1α and contribute to cancer aggressiveness in an oxygen concentration‐independent manner." (PMID 33773069, 2021). "Collectively, these data suggest that targeting HIFAL lncRNA in combination with HIF-1α inhibition emerges as a promising strategy to inhibit cancer growth." (PMID 33637716, 2021). "Consistently, we noted that HIF-1α induced cancer cell invasion, and that the silencing of HIF-1α expression significantly inhibited LPA-induced cancer cell invasion." (PMID 34065317, 2021). "Cancer cells are more hypoxic than normal cells, as determined by increased hypoxia-inducible factor-1α (HIF1α) protein levels." (PMID 34924566, 2021). "Previous investigations have identified an association between chemoresistance and the aberrant expression of many hypoxia mediated genes, which places HIF-1α as a widely accepted therapeutic target for various cancers." (PMID 34081626, 2021). "The compound reduces cancer cells proliferation, survival and migration through multiple signaling pathways, notably via modulation of the NFκB, Keap1/Nrf2 and HIF1α pathways." (PMID 34680439, 2021). "It sheds light on the HIF-1α stabilization in cancer as well as suggests new possibilities of therapeutic angiogenesis." (PMID 34611473, 2021). "Transcription factors, including AP1, PEA3/Ets, SP1, AP2, and the hypoxia-induced factor 1α (HIF1α) mediate uPAR transcription in cancer cells." (PMID 33923400, 2021). "Reduced expression of SIRT3 in cancer cells stimulates ROS production, leading to HIF-1α stability and increased aerobic glycolysis." (PMID 33637686, 2021). "Consistently, inhibition of HIF1α nitrosylation by caveolin-1, a well-known NOS inhibitor, decreases HIF1α activity in a variety of cancer cells." (PMID 34947954, 2021). "Hypoxia is a common phenomenon in the majority of cancers and great interest on HIF-1α stu-dies comes from its potential for targeted therapy through small inhibitors." (PMID 33146980, 2021). "HIF subunit alpha (HIF-1α) regulates various processes and, under hypoxic conditions, can promote cancer cell survival." (PMID 34072826, 2021). "HIF-1α is overexpressed in human cancer as a result of intratumoral hypoxia as well as genetic alterations." (PMID 33069104, 2021). "A few previous studies have shown that BBR inhibited the expression of VEGF and HIF-1α in various cancer cells 30-32." (PMID 34803500, 2021). "Briefly, Pin1 promotes the stability and transcriptional activity of HIF-1α in human cancers or diseases." (PMID 33807199, 2021). "Hypoxia-inducible factor 1-alpha (HIF1α) levels are elevated in cancer cells during hypoxia and HIF1α dimerizes with HIF1β to activate target genes like VEGF." (PMID 35008272, 2021). "Several studies demonstrated that HIF-1A/GLUT1 signaling is related to 18F-FDG uptake among patients with cancer and metabolic disorder." (PMID 33712681, 2021). "In cancer cells, miR-210 is highly prevalent in hypoxic exosomes, which is expressed in an HIF-1α-dependent manner and is involved in navigating metabolic changes, angiogenesis, cell proliferation, migration, invasion, apoptosis, and stemness." (PMID 34444030, 2021).
cancer (continued). "Numerous studies have exhibited the anti-cancer effect of HIF-1α inhibition itself and the augmentation of anti-cancer treatment efficacy by interfering with HIF-1α-mediated signaling." (PMID 34575983, 2021). "Regarding angiogenesis, STAT3 is activated in cancer cells by reactive oxygen species (ROS), mechanistic target of rapamycin complex 1 (mTORC1) and/or IL-6, and further induces hypoxia-inducible factor 1-alpha (HIF-1a) activation during hypoxia." (PMID 34440220, 2021). "This high ROS level stimulates cancer cell progression both by activating cell survival pathways (Akt, mTOR and NF-κB) and by stimulating angiogenesis related to hypoxia (HIF-1α)." (PMID 34827149, 2021). "During hypoxia, STAT3 is activated in cancer cells by ROS, mTORC1, and/or IL-6, and further induces HIF-1a." (PMID 34440220, 2021). "miR-210 inhibitor attenuated the “anti-cancer” effect of sevoflurane and HIF-1α expression induced by sevoflurane, and miR-138 or miR-335 inhibitors reversed the “anti-cancer” effect of desflurane and HIF-1α or MMP9 expressions induced by desflurane." (PMID 33919449, 2021). "As a consequence, HIF-1α and HIF-2α expression have been reported to be associated with poor prognosis and metastasis of multiple human cancers." (PMID 34202979, 2021). "It is known that these two transcription factors, c-Myc and HIF-1α, cooperate to promote cancer cell growth and progression." (PMID 34680439, 2021). "The authors would like to conclude that monotherapy with VOA (G3) and combination therapy with VIN can regulate HIF-1α-guided fatty acid synthesis in cancer cells by activating PHD-2 in vivo." (PMID 34869321, 2021). "Hypoxia activates HIF-1α in solid tumors of mammary glands, which helps in the furbishing of cancer cells even in oxygen scarcity." (PMID 34090331, 2021). "It is confirmed that OLFM4 contributes to cancer cell proliferation, and HIF1α is involved in this process." (PMID 34912753, 2021). "This led to the identification of NPM1 as a direct binding partner of HIF‐1α both in vitro and inside cancer cells." (PMID 34388291, 2021). "Intensive studies have demonstrated that HIF-1α is a metabolic regulator which regulates the transcription of genes involved in aerobic glycolysis or fatty acid synthesis during cancer development and oncovirus infection." (PMID 34055662, 2021). "Several of the transcription factors that interact with Ref-1 have a profound impact on metabolic reprogramming in cancer, including HIF1-α, STAT3, and NRF2 (nuclear factor erythroid 2-related factor 2)." (PMID 34376225, 2021). "Hypoxia‐inducible factor‐1α (HIF‐1α) is often overexpressed and accumulates in cancer cells, in which HIF‐1α‐mediated signalling is a crucial pathway that regulates the metabolism and growth of solid tumours." (PMID 33942488, 2021). "In patients presenting a cancer type with a high level of HIF-1α, a higher mortality rate is observed." (PMID 34436498, 2021). "In this sense, PD-L1 (Programmed death 1 – ligand 1) is an HIF-1α target gene and is upregulated under hypoxia (0.1% O2) in MDSCs, in dendritic cells, as well as in cancer cells." (PMID 34539584, 2021). "Acquired data showed that quercetin promoted therapeutic index of DOX via its opposite effects on HIF-1α in healthy and cancer cells." (PMID 33401572, 2021). "HIF-1α also contributes to the development of platinum resistance through induction of cancer cell autophagy." (PMID 34867818, 2021). "This concept is supported by previous studies showing that Akt acts as an upstream mediator of HIF-1α activation in cancer cells and PASMCs, leading ultimately to increased cell survival, proliferation, and a glycolytic switch." (PMID 34638712, 2021).
cancer (continued). "Our results suggest that memantine activates AMPK1/2 significantly (p=0.039 and p=0.0105) that led cells through apoptosis and autophagy by decreasing cancer cell metabolism regulators like HIF1A, B-catenin and PKM as the consequence of this energetic shift." (PMID 34121969, 2021). "APE1 reduces HIF1α thereby activating its DNA binding capability further regulating HIF1α-dependent cancer metabolic alterations." (PMID 34557865, 2021). "Utilizing its transcriptional activity, HIF-1α affects several cancer properties, including tumorigenesis, apoptosis, genomic instability, metastasis, and invasion, and is therefore important in cancer progression." (PMID 35008634, 2021). "HIF-1α has been found to promote EMT in many human malignancies leading to increased cancer aggressiveness." (PMID 34199634, 2021). "Crosstalk between hypoxic cancer cells secreting VEGF-A under the control of HIF1α and ECs expressing the VEGF receptor 2 (VEGFR2), triggers EC proliferation and migration, thereby leading to enhanced neo-vascularization." (PMID 34205977, 2021). "Inhalational anesthetics accelerated cancer cell malignancy via HIF-1α/miR-138 or -210 in SKOV3 cells." (PMID 33919449, 2021). "Berberine modulates various signaling pathways, including PI3K/Akt, MAPKs, AMPK, STAT3, NF-κB, EGFR, ROS, and HIF-1α, to sensitize cancer cells to a broad spectrum of cancer therapies." (PMID 34576028, 2021). "Unequivocally, HIF-1α has a central role in orchestrating the processes that allow cancer cells (and other diseased cells) to accommodate aerobic glycolysis." (PMID 33466614, 2021). "Hypoxia-inducible factors (such as HIF1A) play an important role in the development of tumors, thus the study of these factors is indispensable for cancer research." (PMID 34895237, 2021). "In cancer, they are found to act as enhancers of HIF-1α and EPAS1 expression and as well regulators of HIF stability and transcriptional activity." (PMID 34444030, 2021). "HIF-1α can particularly induce EMT by upregulating the expression of EMT-TFs in several types of cancers, including lung, colorectal, and head and neck cancers." (PMID 33673417, 2021). "Accordingly, the hybrid metabolic state in cancer cells can be promoted by the stabilization of HIF-1α and elevated production of mitochondrial ROS." (PMID 34381722, 2021). "Upregulation of HIF-1α activates crucial cancer hallmarks such as angiogenesis leading to poor cancer patient prognosis." (PMID 34671207, 2021). "S1P has been reported to form complexes with HIF-1α in the nucleus and to modulate HIF-1α-induced transcription by binding HIF-1α promoter regions and enhancing histone H3 acetylation in different cancer cell lines." (PMID 33430140, 2021). "Cancer cells that are exposed to hypoxic environments accumulate hypoxia-inducible factor 1 Alpha (HIF1α), the primary transcription factor conducting a cell’s response to low oxygen levels." (PMID 34072345, 2021). "Cdk8 kinase activity is required for induction of many Hif1a targets and supports glycolysis in cancer cells." (PMID 33767186, 2021). "Previous studies have shown that SENP1 plays an important role in the occurrence and progression of malignant tumors by regulating hypoxia-inducible factor (HIF)-1α." (PMID 33791211, 2021). "When MiaPaCa2 cells were transferred in athymic mice, emodin and rhein stopped cancer cell growth and HIF-1α expression." (PMID 34073059, 2021). "The list of alkaloid and organosulfur compounds that suppress HIF-1α in cancer (alphabetical order)." (PMID 34575983, 2021). "Accordingly, knockdown of Nrf2 hinders HIF-1α accumulation in hypoxic cancer cells at post-translational levels, which subsequently suppresses the expression of hypoxia-inducible genes including metabolic enzymes." (PMID 34946740, 2021). "While the mechanisms of HIF-1A regulation by hypoxia in cancer are well understood, the role of other microenvironmental factors in modulating HIF-1A has not been characterized." (PMID 34209094, 2021).
cancer (continued). "Several previous studies of human malignant neoplasms have revealed that HIF-1α has a role in the direct regulation of NDUFA4L2 in cancer cells." (PMID 33828084, 2021). "It has been well demonstrated that HIF-1α extensively regulates hypoxia gene expression and aggressive phenotypes of cancer cells, leading to metabolic changes, increased survival, invasion, migration, angiogenesis, and other related signal transduction." (PMID 34335854, 2021). "Under hypoxic conditions, the activity of PHDs and FIH1 on HIF-1α is affected, and metabolic reprogramming in a cancer cell is preferred." (PMID 33809480, 2021). "A view that PKM2 is beneficial to cancer progression is that it acts as a transcriptional co-activator of HIF-1α and regulates the metabolic reprogramming of cancer cells under hypoxic conditions." (PMID 33456577, 2021). "Emerging researches have reported that HIF-1α overexpression contributes to poor prognosis and is a therapy target in diversified cancers." (PMID 35004677, 2021). "The miR-148b and miR-320a target DNA methyltransferase 1 (DNMT1) and hypoxia inducible factor 1 subunit alpha (HIF1α), respectively, which have the potential of promoting cancer cell metastasis and angiogenesis." (PMID 34852849, 2021). "Otto Warburg proposed the relationship between Hif-1α and cancer in 1923 as the “Warburg effect” to explain cells surviving under hypoxic conditions." (PMID 34572451, 2021). "Immunoblotting results indicated the reduction of protein concentration of these genes in both cell lines in dose-dependent manner, revealing modulatory role of taxifolin on critical components of cancer signaling pathways i.e., Hif1-α,VEGF and Akt." (PMID 34113483, 2021). "The interaction between HIF-1α and c-Myc is key to the adaptation of cancer cells to the hypoxic microenvironment and the malignant progression." (PMID 34680439, 2021). "HIF-1α, is a transcription factor that regulates different genes in critical events in cancer development, including angiogenesis, cell survival, glucose metabolism, and invasion." (PMID 34715860, 2021). "Owing to the presence of exogenous Au component and the endogenous knockdown of HIF-1α gene, the RT of cancer cells in vitro is significantly boosted as proven by increased ROS generation and decreased cancer cell invasion and clone formation." (PMID 33408777, 2021). "Lactate can also act as a hypoxia mimetic factor by activating HIF-1α expression in normoxic cancer cells and adjacent endothelial cells." (PMID 34829672, 2021). "HIF1α and HIF2α have different target gene profiles, but their regulation and accordingly their roles can be different in cancer progression." (PMID 34257622, 2021). "Hypoxia-Inducible Factor 1α (HIF-1α), the main regulator of the oxygen homeostasis, promotes cancer cell survival through proliferation, angiogenesis, metastasis and radioresistance." (PMID 34359734, 2021). "Thymoquinone being potent anticancer agent significantly lowers the hypoxia‐inducible factor‐1α (HIF‐1α) expression, inhibits interaction between HSP90 and HIF‐1α, and boosts HIF‐1α protein degradation in hypoxic cancer cells." (PMID 33747489, 2021). "In line with this, HIF-1α/p300/p-STAT3 axis is considered a therapeutic target to eradicate cancer progression." (PMID 34692527, 2021). "OPN binds to its receptor integrin αvβ3 to induce autophagy via sustaining FoxO3a stability and to promote cancer stem cell-like phenotype through NF-κB/HIF-1α signaling." (PMID 33562077, 2021). "Contrastingly, in human cancers, a subset of HIF1A targets involved in remodeling of the extracellular matrix is consistently associated with poor prognosis." (PMID 33654095, 2021). "Based on this, we silenced the HIF-1α gene using RNAi to determine the effect of RNAi technology combined with ASP on cancer angiogenesis and provide an experimental basis for comprehensive clinical anticancer therapy using such combinations." (PMID 34335854, 2021).
cancer (continued). "The experimental evidence that melatonin, at both physiological and pharmacological concentrations, inhibits HIF-1α comes primarily from publications where melatonin/HIF-1α interactions were examined in cultured cancer cells." (PMID 33466614, 2021). "Hypoxia-inducible factor-1 (HIF-1α) is an essential regulatory factor for aerobic glycolysis and other neoplastic bioprocesses in cancer cells in both hypoxic as well as oxygenated regions of tumors." (PMID 35096814, 2021). "This notion is supported by the evidence showing that HIF1α is a critical driver of the Warburg effect and that leptin stabilizes HIF1α in cancer cells." (PMID 33535537, 2021). "In this study, we aimed to clarify the relationship between hZIP1, HIF-1α, and cancer cell energy metabolism." (PMID 34926261, 2021). "In this work, we provide a valuable resource for investigating context-dependent roles of HIF1A and its targets in cancer biology." (PMID 33654095, 2021). "We discovered a novel mechanism of regulation of HIF-1α, involving Smurf2 E3 ubiquitin ligase, in CDK4/6 inhibitor treated cancer cells where HIF-1α is destabilized." (PMID 34611473, 2021). "In most cases, cancer cells exhibit dysfunctional mitochondrial enzymes favoring oncogenic effects, affecting hypoxia-inducible factor 1 (HIF-1α) activation as well as genomic instability (via ROS production and mutations of mtDNA)." (PMID 34681703, 2021). "Hypoxia inducible factor-1α (HIF1α), an adaptive gene of hypoxia condition, played an important role in affecting chemotherapy sensitivity for many cancer types and various therapeutic regimens." (PMID 34595177, 2021). "In the past decades, the transcription factors (TFs) aryl hydrocarbon receptor (AHR) and hypoxia inducible factor-1α (HIF-1α) have been recognized to strongly impact cancer progression and escape mechanisms." (PMID 34572746, 2021). "In vitro reporter assays showed that perillyl alcohol efficiently blocks the transcriptional activity of HIF-1α in several types of cancer cells treated with CoCl2." (PMID 34575983, 2021). "Previous studies showed that HIF-1α involved in cancer cell metabolism by regulating HK2, GLUT1, and others." (PMID 34238918, 2021). "The research from Lau and his colleagues reported an inter-relationship that AKT/HIF-1α/PDGF-BB autocrine loop mediated hypoxia-induced chemoresistance in cancer cells." (PMID 34445528, 2021). "HIF-1α also promotes both glycolytic energy metabolism and angiogenesis and participates in the poor cancer prognosis." (PMID 34070746, 2021). "Such correlation was stronger with WWOX/HIF1A suggesting that WWOX modulates HIF1A function similarly to cancer cells." (PMID 33520443, 2021). "For example, S-nitrosylation of HIF-1α at Cys533 elevates the activity, resulting in the increased expression of various angiogenic factors that stimulate angiogenesis and promote cancer metastasis." (PMID 33925645, 2021). "Our results indicated that the increased expression of HIF-1a contributes to the changes in the expression profiles of significant genes and miRNAs involved in cancer cell apoptosis and proliferation." (PMID 34181359, 2021). "HIF-1α (Hypoxia-inducible factor-1α) is a key nuclear transcription factor mediating hypoxic response of cancer cells, which can promote metabolism, angiogenesis and proliferation of cancer cells in hypoxic environment." (PMID 33754005, 2021). "The elevation of HIF-1α after UPR activation explains at least in part the induction of C/EBPδ in p97-inhibited cancer cells." (PMID 33731668, 2021). "BHLHE40 role in cancer is unclear although some studies reported the activation of its expression directly by HIF1α in a variety of cancer cells." (PMID 33602983, 2021). "HIF-1α is an oxygen-labile DNA-binding transcriptional activator and regulates cancer cell proliferation and invasion." (PMID 33919449, 2021).